GOPC (golgi associated PDZ and coiled-coil motif containing)
Description:
Plays a role in intracellular protein trafficking and degradation. May regulate CFTR chloride currents and acid-induced ASIC3 currents by modulating cell surface expression of both channels (By similarity). May also regulate the intracellular trafficking of the ADR1B receptor. May play a role in autophagy (By similarity). Together with MARCHF2 mediates the ubiquitination and lysosomal degradation of CFTR. Overexpression results in CFTR intracellular retention and lysosomaldegradation in the lysosomes.
Synonyms: PIST; CAL; FIG; dJ94G16.2; GOPC1
Tractability: Small molecule: a structure with a bound ligand is known. Antibody: its Gene Ontology location is reachable by antibodies, with high confidence; UniProt places it where antibodies can reach, with medium confidence. PROTAC: ubiquitination databases record sites on it; its protein half-life has been measured; a small molecule that binds it is known.
Gene: Protein-coding gene on chromosome 6 (117,560,269 to 117,602,542, reverse strand). Ensembl gene ENSG00000047932.
Subcellular location: Cytoplasm; Golgi apparatus membrane; Golgi apparatus, trans-Golgi network membrane; Synapse; Postsynaptic density; Cell projection, dendrite
Subcellular location (Human Protein Atlas): Golgi apparatus; Calyx; Connecting piece; Mid piece; Principal piece
Pathways (Reactome):
Signal Transduction: RHO GTPases regulate CFTR trafficking; RHOQ GTPase cycle
Gene Ontology:
Molecular function: identical protein binding; molecular sequestering activity; protein binding; transmembrane transporter binding; frizzled binding; GTPase regulator activity; protein homodimerization activity
Biological process: negative regulation of anion channel activity; negative regulation of protein localization to cell surface; apical protein localization; endoplasmic reticulum to Golgi vesicle-mediated transport; Golgi to plasma membrane transport
Cellular component: cytoplasm; Golgi apparatus; Golgi membrane; membrane; protein-containing complex; trans-Golgi network transport vesicle; Golgi-associated vesicle membrane; lysosomal membrane; plasma membrane; dendrite; postsynaptic density; synapse
Genetic constraint (gnomAD): Loss-of-function variants: 22 observed, 38.65 expected, observed/expected ratio (o/e) 0.57, 90% interval 0.41 to 0.81. The upper end of that interval is the gene's LOEUF score, 0.81, which puts it in group 3 of 6, group 1 being the genes least tolerant of losing a copy. Missense variants: 343 observed, 463.03 expected, observed/expected ratio (o/e) 0.74, 90% interval 0.68 to 0.81. Synonymous variants: 154 observed, 172.13 expected, observed/expected ratio (o/e) 0.89, 90% interval 0.78 to 1.02.
Homologues: Orthologues: chimpanzee GOPC (99% identical), pig GOPC (97% identical), dog GOPC (96% identical), rabbit GOPC (96% identical), guinea pig GOPC (94% identical), rat Gopc (91% identical), mouse Gopc (91% identical), tropical clawed frog gopc (82% identical), zebrafish gopc (76% identical), Caenorhabditis elegans gopc-1 (47% identical).
Diseases named in the same sentence as GOPC in open-access papers:
GOPC is named in the same sentence as 25 diseases in open-access papers, as found by Europe PMC text mining. Sharing a sentence is not in itself a finding about the gene and the disease. The quoted sentences say what the papers report.
Globozoospermia (8 papers, 2015 to 2024). Any structural anomaly of the acrosome resulting in a round sperm head. "It has been demonstrated that male mice deleting gene encoding Golgi-associated PDZ- and coiled-coil motif-containing protein (GOPC) are infertile and show globozoospermia with a coiled tail around the nucleus." (PMID 26436098, 2015). "A previous study has demonstrated that GOPC-deficient males are infertile with globozoospermia." (PMID 28055014, 2017). "CCDC62 contains coiled-coil domains similar to PICK1 and GOPC, whose knockout mouse models display also globozoospermia." (PMID 31985809, 2020). "Knockout mice approach for different purposewhich later exhibited globozoospermia manifestation.The target genes were as: Csnk2a2, GOPC, Gba2,PICK1, iii." (PMID 30291685, 2019). "GOPC is involved in PAG transport from Golgi network to acrosome and its absence (GOPC-/) is associated with globozoospermia." (PMID 30291685, 2019). "The images that we obtained show significant similarities to those described in GOPC knockout mice, an animal model of globozoospermia." (PMID 26436098, 2015).
glioblastoma (5 papers, 2011 to 2020). The most malignant astrocytic tumor (WHO grade IV). "The GOPC/FIG (Fused In Glioblastoma) gene also resides on the short arm of chromosome 6 and encodes a protein displaying coiled-coil and PDZ domains." (PMID 30719217, 2019). "A literature review of these genes reported that ROS1 and GOPC are partners in an oncogenic fusion gene found in the glioblastoma cell line U118MG, created by a 240 kb intrachromosomal deletion." (PMID 22163003, 2011).
glioma (3 papers, 2022 to 2023). A benign or malignant brain and spinal cord tumor that arises from glial cells (astrocytes, oligodendrocytes, ependymal cells). "Beyond these, in adult gliomas, the main partner of ROS1 fusions is GOPC." (PMID 37584407, 2023). "GOPC, a protein that containing a coiled helix motif, is also one of the prognostic markers of Early-Stage Lung Squamous Cell Carcinoma, and when fused with ROS1 and other ROS1, it can represent a rare but recurrent drug target in various glioma types." (PMID 35859893, 2022).
melanoma (2 papers, 2020 to 2025). A malignant, usually aggressive tumor composed of atypical, neoplastic melanocytes. "In melanoma cells, the elevated genes included MAP2K7, RIOK1, GOPC, KHDC4 and PDPK1, which may be associated with stress/drug resistance, protein synthesis, and the regulation of cellular migration." (PMID 41383633, 2025).
cystic fibrosis (1 paper, 2012). Autosomal recessive disorder caused by pathogenic variants in the CFTR gene (cystic fibrosis transmembrane conductance regulator), which encodes a chloride and bicarbonate channel expressed in epithelial cells, and follow the diagnosis criteria. "GOPC, a coiled-coil motif and PDZ containing protein, negatively regulates CFTR, mutations in which result in cystic fibrosis." (PMID 23210427, 2012).
hepatic cancers (1 paper, 2019). "This database analysis highlights the previously unknown involvement of ROS1 and GOPC copy number alterations in soft tissue sarcomas and hepatic cancers." (PMID 30719217, 2019). "Although this is the first report of ROS1-GOPC fusion in HAS, database analysis highlights the previously unknown frequency of ROS1 and GOPC molecular alterations in soft tissue sarcomas and hepatic cancers." (PMID 30719217, 2019).
soft tissue sarcoma (1 paper, 2019). A malignant neoplasm arising from muscle tissue, adipose tissue, blood vessels, fibrous tissue, or other supportive tissues excluding the bones. "To further explore the incidence of ROS1 and GOPC concurrent alterations in primary hepatobiliary tumors and soft tissue sarcomas, we queried available datasets in cBioportal." (PMID 30719217, 2019).
cancer (9 papers, 2011 to 2023). A tumor composed of atypical neoplastic, often pleomorphic cells that invade other tissues. "First, the subinteractomes of these ORF proteins contain proteins associated with ‘cancer hallmark’ and oncoproteins (e.g., the case of C5orf24 and its protein partners XPO1, PBX1, MYC, CIC, GOPC, CREB1 and STK11)." (PMID 37373333, 2023). "We describe the first case of HAS harboring a fusion of ROS1 with GOPC/FIG and review of the role of ROS1 rearrangements in cancer and evidence supporting the use of therapeutics that target ROS1." (PMID 30719217, 2019). "Actually, studies on the role of GOPC, PAEP and IDE in STAD are mostly lacking, but they all have important roles in other cancer types." (PMID 35859893, 2022).
infection (5 papers, 2013 to 2020). The state of being infected such as from the introduction of a foreign agent such as serum, vaccine, antigenic substance or organism. "Moreover, it was determined that HeLa cell infection with oncolytic measles virus is associated with the autophagosome accumulation via the engagement of the CD46-Cyt-1/GOPC pathway." (PMID 31217023, 2019). "Nevertheless, our results indicate that CD46-cyt1 and GOPC play an important role in the autophagy response to Ngo-infection." (PMID 30753248, 2019). "Autophagy is induced through the CD46-cyt1/GOPC pathway and this response kills Ngo invading cells early in infection." (PMID 30753248, 2019). "Taken together, these results indicate that the autophagic response to Ngo infection is initiated by CD46-cyt1/GOPC." (PMID 30753248, 2019). "Among these interactions, the alleged targeting of GOPC (Golgi-associated PDZ and coiled-coil motif-containing protein) by MeV-C does not influence the infection-induced autophagy." (PMID 31217023, 2019). "In addition, MeV induces autophagy through the CD46-Cyt-1/GOPC pathway, which indicates that a cell surface pathogen receptor can directly trigger autophagy, a critical step for controlling infection." (PMID 30067475, 2018). "Immediately upon infection, attenuated measles virus induces a first transient wave of autophagy, via a pathway involving its cellular receptor CD46 and the scaffold protein GOPC." (PMID 24086130, 2013). "In addition, the classical swine fever virus NS2 protein bound GOPC in a yeast two-hybrid screen, although it has not yet been determined whether GOPC is degraded during infection with this virus." (PMID 33027661, 2020). "We show that pUL56 binds directly to the coiled-coil region of GOPC, is necessary for the proteasome-mediated degradation of GOPC in HSV-1-infected cells, and is sufficient to promote GOPC degradation in the absence of infection." (PMID 33027661, 2020).
tumor (5 papers, 2011 to 2024). "Six rare fusion partners were also identified: GOPC, MPRIP, NUP210L, ZCCHC8, CCDC6, and CFAP53, each present in one tumor." (PMID 38835380, 2024). "Initial findings indicated that RANGAP1, GOPC, NHLRC3, FZD6, and IDE were significantly correlated with stem cell indices and tumor microenvironment parameters." (PMID 35859893, 2022). "Fusion partners that participate in ROS1 rearrangements include CD74, SLC34A2, SDC4 in addition to GOPC/FIG, which was observed in this patient's tumor." (PMID 30719217, 2019). "This is consistent with observation that both LMP tumours harbor allelic imbalance of the chr6q arm which include the ROS1, DCBLD1, and GOPC loci." (PMID 22163003, 2011).
CNS tumors (2 papers, 2011 to 2024). "Six different ROS1 fusion partners have already been described in pediatric CNS tumors (+/−7% of pediatric CNS tumors): GOPC, ARCN1, CHCHD3, ZCCHC8, TPR and CEP85L." (PMID 39409964, 2024).
GOPC also shares sentences with these, for which no sentence is quoted: cholangiocarcinoma (2 papers); acephalic spermatozoa syndrome (1); acral lentiginous melanoma (1); anaplastic astrocytoma (1); astrocytoma (1); breast carcinoma (1); infertile (1); Lung Squamous Cell Carcinoma (1); male infertility (1); non-small cell lung carcinoma (1); ovarian carcinoma (1); ovarian serous tumor (1); skin cancer (1); thymoma (1).